ITGB3 (integrin subunit beta 3)
Diseases named in the same sentence as ITGB3 in open-access papers (continued):
Sharing a sentence is not in itself a finding about the gene and the disease.
breast cancer (continued). "Next, we focused on the protein expression levels of Itgav, Itgb3, and Vcam1, as they exhibited a progressive increase during mouse cSCC progression and had previously been associated with different EMT transition states in EpCAM− skin and breast cancer cells." (PMID 39075581, 2024). "IL-32 is mainly derived from CAFs, whereas ITGB3 is upregulated during EMT in breast cancer cells." (PMID 37217855, 2023). "Conditional knockdown of ITGB3 revealed its involvement in osteolysis in breast cancer." (PMID 36897488, 2023). "However, in our results, we found EVs with sizes smaller than 1 μm; small EVs are also reported as potential carriers of key integrins in the development of metastases, such as the integrin ITGB3, which can favor communication between breast cancer cells." (PMID 37047783, 2023). "Similarly, the NRP-1 knockout MDA-MB-231 cells displayed a significant decrease in the levels of integrin β3 (ITGB3), another extracellular adhesion protein well-known to enhance lung and bone metastasis of breast cancer cells once upregulated." (PMID 37175499, 2023). "Simultaneously, MIIP was negatively correlated with ITGB3 in expression in breast cancer." (PMID 36130933, 2022). "In addition, the miRNA-mediated reduction of cellular ITGB3 synthesis in MDA-MB-231 cells is associated with partial and complete remissions of both, soft tissue and osteolytic lesions in a nude rat model for breast cancer skeletal metastasis." (PMID 33083904, 2021). "Here, the downregulation of SEPT11 after ITGB3 knockdown could explain the decreased migration activity of the breast cancer cells used, due to impairment of the cytokinesis/cytoskeletal dynamics." (PMID 33083904, 2021). "ITGB3 has a role in breast cancer skeletal metastasis via gene expression modulation, as mirrored for ITGB3 in exosomes, thus it could serve as target for anti-metastatic therapy." (PMID 33083904, 2021). "Therefore, we created two MDA-MB-231 breast cancer cell clones with conditional doxycycline-dependent miRNA-mediated ITGB3 knockdown." (PMID 33083904, 2021). "Therefore, we suggest that ITGB3 has a vital function related to the progression of breast cancer cells, as this protein is instrumental for local and distal effects, mediated by direct contact or via exosomes." (PMID 33083904, 2021). "Moreover, MDA-MB-231 breast cancer cells incubated with these exosomes in vitro showed an increased ITGB3 production." (PMID 33083904, 2021). "Here the authors describe thus far unknown roles of ITGB3 in the uptake of extracellular vesicles, required for colony growth of breast cancer cells." (PMID 32848136, 2020). "Basal-B lines were characterized by markers associated with aggressive tumor features, including PLAT (plasminogen activator) and TGFB1, as well as marker phenotypes associated with normal breast and breast cancer progenitor/stem cells (MUC−/CALLA+; CD44+/CD24−/low; and ITGB3(CD61)+)." (PMID 19582160, 2009). "Overall, the combined evidence from this and previous reports indicates that ITGB3 Leu33Pro heterozygosity and homozygosity do not increase the risk of breast cancer." (PMID 15970922, 2005). "The combination of cilengitide with trastuzumab produced a synergistic effect, leading to the most significant reduction in migration markers, indicating that dual targeting of HER2 and ITGB3 could be an effective strategy to limit metastasis in Trastuzumab-resistant HER2-positive breast cancer." (PMID 39857240, 2024). "However, a separate in vitro study showed that breast cancer cell lines with higher expression of ITGB3 were resistant and could be sensitized by knockdown of ITGB3 to lower levels." (PMID 39707454, 2024). "Given the observed association between ITGB3 expression and TGF-β activity, we investigated the therapeutic potential of the ITGβ3 inhibitor, cilengitide, and its effect on TGF-β signalling in Trastuzumab-resistant HER2-positive breast cancer cell lines, SKBR3-R and HCC1954-R." (PMID 39857240, 2024).
breast cancer (continued). "Moreover, we hypothesize that exosomes from breast cancer cells with conditional knockdown of ITGB3 having low levels of this protein, possess a reduced capacity to modulate the pre-metastatic niche and are critical for cancer cell survival and tumor growth." (PMID 33083904, 2021). "Increased expression of ITGB3 could promote and control the metastasis of breast cancer and EC." (PMID 32315343, 2020). "Thus, the central role of ITGB3 in intracellular communication via EVs and the proposed function of EVs in cancer metastasis might explain the requirement for ITGB3 in breast cancer metastasis." (PMID 32848136, 2020). "Moreover, in MCF-7 breast cancer cells, calcitriol has shown to inhibit Itgb3 gene expression." (PMID 31698751, 2019). "Additionally, inhibition of ITGB3 could functionally abolish the pro-malignant changes in breast cancer cells." (PMID 27374079, 2016). "Future research should no longer focus on risk of breast cancer in ITGB3 Leu33Pro homozygotes, but should rather try to examine other cancer subgroups like ovarian cancer, melanoma or yet other cancer subgroups, as explanations for the increased overall cancer risk in Leu33Pro homozygotes." (PMID 15970922, 2005). "Although a direct link between ITGB3 and CTC clusters is unreported, its elevated expression correlates with poorer survival in breast cancer patients." (PMID 41423632, 2025). "In contrast, we were not able to find a relationship between cilengitide sensitivity and cilengitide target integrins ITGAV, ITGB3, or ITGB5, contrary to previous observations in breast cancer cell lines and glioblastoma." (PMID 39707454, 2024). "This study delves into the interplay between ITGB3 expression and TGF-β signalling in Trastuzumab-resistant HER2-positive breast cancer cells." (PMID 39857240, 2024). "In our previous study, increased ITGB3 gene expression was observed, indicating its involvement in regulating stemness through the Notch pathway in HER2-positive breast cancer cell lines." (PMID 39201327, 2024). "Only relevant research has revealed that Integrin Subunit Beta 3 (ITGB3) affects energy metabolism through the expression of the ISCA1 gene, which has a role in breast cancer bone metastases." (PMID 36072584, 2022). "NFATC1 binds to the ITGB3 promoter in osteoclast precursor cells, while NFATC2 and NFAT5 promote ITGA6/ITGB4-mediated cell invasion in breast cancer." (PMID 31730483, 2019). "Having validated that ITGB3 was upregulated at the protein level in HPP and also under hypoxic conditions alone, we explored putative functional roles of ITGB3 in breast cancer progression, particularly under low-oxygen conditions." (PMID 29383126, 2017). "Previous reports do however suggest coordinated transcriptional regulation of ITGAV and ITGB3 genes, including a recent study that demonstrates inhibition of ITGAV and ITGB3 transcription by Myc in a breast cancer model." (PMID 26918447, 2016). "MDA-MB-231 breast cancer cell lines express high levels of ITGA2 / ITGB1, ITGA3 / ITGB1, ITGA5 / ITGB1, ITGAV / ITGB3 integrins, compared to MCF-7, T47D, and ZR75-1 breast cancer cells." (PMID 25593998, 2014). "The induction of pro-apoptotic ITGB1 and ITGB3 by CuB treatment suggests activation of integrins mediated cell death by CuB in MDA-MB-231, SKBR3 and 4T-1 breast cancer cells." (PMID 24729020, 2014). "Basal-B lines predominantly express CD44+/CD24−/low and MUC−/CALLA+ phenotypes characteristic of stem or bipotent progenitor cells, as well as ITGB3 (CD61), also recently characterized as a cancer stem cell marker in MMTV-wnt-1 induced murine breast cancer." (PMID 19582160, 2009). "The uptake of extracellular vesicles and/or quasi-enveloped particles is likely to be mediated by different integrins depending on the cellular background, as e.g. ITGB3 but not ITGB1 is critical for EV uptake in the breast cancer cell line MDA.MB.23179,80." (PMID 40571699, 2025).
breast cancer (continued). "The results suggest that targeting ITGB3, alone or in combination with cilengitide, may offer a promising strategy to resensitize resistant HER2-positive breast cancer cells to Trastuzumab." (PMID 39857240, 2024). "Supporting this hypothesis, depletion of ITGB3, ITGB4 and ITGB5 reduced angiogenesis and tumor growth in breast cancer." (PMID 37215577, 2023). "Secondly, in MDA-MB-231 breast cancer cells, it was shown that cAMP direct elevation reduced leptin-induced cell migration, via both cAMP/PKA- and cAMP-Epac-dependent pathways, and was related to a down-regulation of ITGB3 and FAK proteins level." (PMID 37904233, 2023). "Therefore, we analyzed the presence of ITGB3 also in exosomes produced by MDA-MB-231 cell clones with conditional integrin β3 knockdown, as well as in exosomes isolated from plasma of rats with breast cancer skeletal metastasis." (PMID 33083904, 2021). "In this study, we found that ITGB3 knockdown led to a progressive decrease in RRM2 levels, hence we suggest that ITGB3 might be a driver protein for this breast cancer-related protein." (PMID 33083904, 2021). "In this regard, we demonstrate here that unlike in breast cancer, where TGFβ cooperates with ITGB3-specific ECM proteins, TGFβ preferentially cooperates with ITGA1-specific collagens in PDAC to promote EMT, therapy resistance and metastasis." (PMID 28855593, 2017). "In contrast, in several transgenic mouse models of breast cancer, the consensus is that the CD24+/High sub-population rather than CD24Neg/Low sub-population enriches for TIC activities when CD24 is paired with either CD29 (ITGB1) or CD61 (ITGB3)." (PMID 27001172, 2016). "With minimal toxic effects, we have for the first time identified ICJ as the potent metastatic inhibitor in breast cancer by specifically targeting TβRII: ITGB3: FAK: p38, the central pathway for non-canonical TGF signaling." (PMID 27374079, 2016). "Moreover, assessment of breast cancer stem or luminal progenitor cell biomarkers showed positivity in most LAM tissue for the aldehyde dehydrogenase 1 (ALDH1), integrin-ß3 (ITGB3/CD61), and/or the sex-determining region Y-box 9 (SOX9) proteins." (PMID 26167915, 2015). "The heterogeneous expression of ITGB3 among resistant cell clones suggests that targeting this integrin could be an effective strategy to overcome resistance and improve outcomes in HER2-positive breast cancer." (PMID 39857240, 2024). "However, the effect of NRP-1 overexpression on the ITGB3 signaling pathway and its role in chemoresistance in breast cancer has not yet been investigated." (PMID 29728077, 2018). "Despite these insights, the role of ITGB3 in EMT and Hedgehog signaling in HER2-positive breast cancer has not been previously explored." (PMID 39201327, 2024).
COVID-19 (32 papers, 2020 to 2025). A disease caused by infection with severe acute respiratory syndrome coronavirus 2. "In the present study, ITGA2B and ITGB3 were identified as key genes for COVID-19-related stroke, and these biological processes were closely associated with COVID-19-related stroke." (PMID 35557984, 2022). "The study on the association of 16 polymorphisms in genes encoding prothrombotic and cardiovascular risk factors with COVID-19 disease severity demonstrated that integrin beta-3 (ITGB3) PIA1/A2 polymorphism was independently associated with the increased risk for severe COVID-19." (PMID 35955824, 2022). "Of these transcripts, ITGB3 was one of the vital predictive genes of COVID-19-related stroke as involved in integrin pathway signal transduction." (PMID 38077346, 2023). "Most crucially, ITGA2B and ITGB3 were shown to be the hub genes for key stroke-related modules, suggesting that they play critical roles in COVID-19-related stroke." (PMID 35557984, 2022). "Therefore, platelet activation, ECM-receptor interaction, PI3K-Akt signaling pathway, and hematopoietic cell lineage may represent the potential biological processes associated with COVID-19-related stroke, and ITGA2B and ITGB3 may be potential intervention targets for COVID-19-related stroke." (PMID 35557984, 2022). "As a result, ITGA2B and ITGB3 have been identified as important genes involved in COVID-19-related stroke." (PMID 35557984, 2022). "Furthermore, ACE2 expression (angiotensin−converting enzyme 2) as the key host protein of COVID-19, correlates with expression levels of ITGB3 in post-mortem lung tissues obtained from patients who died from COVID-19 ARDS." (PMID 36776845, 2023). "In COVID-19, ITGB3 is indicative of a large number of megakaryocytes in the pulmonary circulation." (PMID 36776845, 2023). "Comprising platelet activation, coagulation and wound healing GO terms and platelet-associated genes such as MYL9, ITGB3, GP1BB, TBXA2R and GP6, expression of the Magenta module increased modestly over time and was consistently higher in patients with severe COVID-19." (PMID 37365222, 2023). "ITGA2B and ITGB3 have been further identified as crucial genes of COVID-19-related stroke." (PMID 35557984, 2022). "The most significantly upregulated protein we identified was ITGB3 (logFC = +3.32 to +4.78), which has recently been shown to be upregulated in COVID-19 patient lung samples and has been hypothesized to be an alternative receptor for the SARS-CoV-2 virus." (PMID 35337019, 2022). "In addition, ITGA2B and ITGB3 were obtained by crossing these common genes with the hub genes of stroke-related crucial module, suggesting that these two genes are more crucial than other common genes in the mechanisms of COVID-19-related stroke." (PMID 35557984, 2022). "We found that PDE5A, ITGB3, CEACAM8, and BPI were hub-shared genes in IS and COVID-19, which were remarkably enriched in pathways such as ECM-receptor interaction and focal adhesion pathways." (PMID 37090981, 2023). "The expression of cell-specific genes such as FCER1A in monocyte-derived dendritic cells, PPBP in megakaryocyte, ITGB3 in NK cells, and PF4 in T cells of COVID-19 patients was obviously lower than that in healthy controls." (PMID 36403042, 2022). "Additionally, ITGA2B and ITGB3 may be promising intervention targets for COVID-19-related stroke." (PMID 35557984, 2022). "Integrin-related genes, including ITGA1, ITGB3, ITGB5, and ITGB8, have been less investigated in patients with COVID-19 myocarditis and may be potential prognostic biomarkers." (PMID 39026189, 2024).
melanoma (32 papers, 2005 to 2025). A malignant, usually aggressive tumor composed of atypical, neoplastic melanocytes. "The expression of ITGB3 RNA was linked with prolonged survival of melanoma patients, supporting its potential role as an effector in the metastasis suppressor function of NME1." (PMID 39796775, 2025). "ITGB3 is associated with melanoma progression and metastasis-promoting potential as its overexpression causes melanoma cells to transition from the radial growth phase to the vertical growth phase." (PMID 39796775, 2025). "As a marker and important regulator of senescence, integrin subunit β3 (encoded by ITGB3) was previously reported to drive the distant metastasis of melanoma." (PMID 40864319, 2025). "The integrin B3, encoded by ITGB3, is also widely known to be overexpressed in melanoma and other solid tumors, and its expression is inhibited by let7a binding to the 3′ untranslated region (3′ UTR) of ITGB3." (PMID 29112174, 2017). "Moreover, the loss of let-7a leads to an upregulation of ITGB3 indicating involvement in melanoma development and progression." (PMID 34073664, 2021). "Melanoma cells express ITGB3 preferentially metastatic to the lungs, whereas melanoma cells expressing ITGB1 preferentially metastasize to lymph nodes." (PMID 38279122, 2024). "This is the first study to report on the association between ITGB3, ITGA5, PAI1, and p21 expression and TGF-β activation in BRAFV600E vemurafenib-resistant melanoma cells and to compare parental and resistant cells in this manner." (PMID 39063187, 2024). "In melanoma, ADAR1 controls the expression of integrin beta 3 (ITGB3), a cell surface protein associated with tumor invasion, via miR-22 and PAX6 transcription factor at the post-transcriptional and transcriptional levels." (PMID 35898396, 2022). "It has been reported that integrin subunit beta 3 (ITGB3) is positively related to a higher frequency of malignant melanomas than benign lesions, and insulin-like growth factor 1 receptor was found to be involved in adaptive bypass of BRAFV600E inhibition." (PMID 34106558, 2021). "Due to the strong association of ITGB3 with the ability to convert non-invasive RGP melanoma to an invasive VGP melanoma, the biochemical mechanisms that regulate ITGB3 expression in cancer cells are of substantial interest." (PMID 29855470, 2018). "Here we provide substantial evidence on the role of ADAR1 in melanoma cell invasion by controlling ITGB3 expression independently of RNA editing, at the transcriptional and post-transcriptional levels." (PMID 29855470, 2018). "Silencing of ADAR1 in melanoma cells upregulated ITGB3 expression, thus promoting melanoma malignancy." (PMID 30585209, 2018). "In conclusion, these experiments show that ADAR1 regulates ITGB3 expression and therefore invasion of melanoma cells independently of RNA editing, but the mechanism still depends on the specific RNA-binding capacity of ADAR1." (PMID 29855470, 2018). "Collectively, these results show that miR-22 directly regulates ITGB3 expression and consequently the invasiveness of melanoma cells." (PMID 29855470, 2018). "In summary, here we provide substantial evidence for a model, in which ADAR1 controls the expression of ITGB3 in melanoma cells in several distinct RNA-editing-independent mechanisms, and thereby their invasive phenotype." (PMID 29855470, 2018). "Here, the authors show an ADAR1-dependent and RNA-editing-independent regulation of melanoma invasion mediated by ITGB3 expression, which can be reversed when ITGB3 is blocked." (PMID 29855470, 2018). "In the current study, we identified ITGB3 as mediator of ADAR1 regulation of melanoma cell invasion." (PMID 29855470, 2018). "Our data not only outline ADAR1 and ITGB3 interrelations but more importantly demonstrate ITGB3 key role in ADAR1-induced invasion in melanoma." (PMID 29855470, 2018). "ITGB3, on the other hand, showed apoptosis inducing property in ovarian cancer, gliomas and melanoma." (PMID 27806706, 2016).